RNU6-88P (RNA, U6 small nuclear 88, pseudogene)
Gene: Small nuclear RNA gene on chromosome 10 (12,116,280 to 12,116,379, reverse strand). Ensembl gene ENSG00000272507.
Homologues: Orthologues: chimpanzee U6 (99% identical), macaque U6 (94% identical), guinea pig U6 (77% identical), dog U6 (73% identical), mouse Gm22960 (71% identical), mouse Gm25819 (67% identical), rat LOC120095718 (65% identical), guinea pig U6 (59% identical). Paralogues in human: RNU6-847P (82% identical), RNU6-1084P (81% identical), RNU6-144P (81% identical), RNU6-214P (81% identical), RNU6-684P (81% identical), RNU6-1179P (80% identical), RNU6-1260P (80% identical), RNU6-333P (80% identical), RNU6-98P (80% identical), RNU6-1158P (79% identical), RNU6-1214P (79% identical), RNU6-21P (79% identical), and 1285 more.